IGFBP3 (insulin like growth factor binding protein 3)
Diseases named in the same sentence as IGFBP3 in open-access papers (continued):
Sharing a sentence is not in itself a finding about the gene and the disease.
Obesity (continued). "Interestingly, gene expression dynamics of GHR, IGF-1 and IGFBP-3 was diminished in children with overweight/obesity compared to lean children." (PMID 36384443, 2022). "Furthermore, we assessed if gene expression of GHR, IGF-1 and IGFBP-3 in AT cells is related to overweight/obesity and AT function." (PMID 36384443, 2022). "This suggests that obesity has little impact on total IGFBP-3 levels in our study subjects." (PMID 34239560, 2021). "Important interactions have been observed between IGFBP3, vitamin D metabolism and obesity." (PMID 34391409, 2021). "In addition to the significant differences observed in serum adipokines, fasting glucose levels, insulin levels, and glucose tolerance, obesity was also associated with elevated serum levels of IGF-1, IGF-1/IGFBP2, and IGF-1/IGFBP3 in HFD-Obese mice." (PMID 30867005, 2019). "We have shown that the growth-stimulatory effect of obesity is enhanced in the absence of host-derived IGFBP-3, where high-fat feeding causes increased tumor growth relative to chow diet." (PMID 27448965, 2016). "Despite reports of various effects of obesity on IGFBP3, C-peptide and IGF-1, BMI was not independently associated with cancer outcomes once the effect of serum C-peptide was adjusted." (PMID 23405181, 2013). "This approach revealed that most of the components of the GH/insulin/IGF1 regulatory axis are present in PGs, where their expression pattern is altered under obesity conditions and after an acute insulin treatment (e.g. Igfbp3), which might have some pathophysiological implications." (PMID 28244645, 2017). "Since IGFBP-3 inhibits adipocyte maturation in vitro, it may influence the development of obesity." (PMID 27448965, 2016). "Briefly, an inverse correlation between IGF-1 (IGF-1/IGFBP-3 ratio) circulating levels and several markers for obesity, MetS, T2D, and CVD has been found; and thus, it could indicate that low circulating levels of IGF-1 can lead to MetS and raise the risk for CVD and T2D." (PMID 26733412, 2016). "We show that obesity impairs the exercise‐induced increase in serum total IGF‐1 and IGFBP‐3 concentrations." (PMID 40574473, 2025). "Nevertheless, the correlations found between SIRT1 and IGFBP3 and between SIRT1 and tumor stage in obese CRC patients bolster its possible role in the progression of obesity-related CRC." (PMID 38704452, 2024). "Obesity leads to enhanced circulating levels of insulin, IGF-I, IGF-II and IGF-binding proteins (IGFBP-3), while reducing levels of the low molecular weight IGF-binding proteins (IGFBP-1, IGFBP-2)." (PMID 38260836, 2023). "Early-pubertal girls with obesity also had significantly higher values (p < 0.05) for BMI-SDS, leptin, IGF-1, IGFBP3, insulin and HOMA-IR, LH, ratio LH/FSH, ACTH, DHE-S, androstenedione, testosterone and free testosterone levels than control group." (PMID 35412268, 2022). "In adults with obesity and/or MAFLD, serum IGF1 levels were lower in those with higher degrees of inflammation and higher stage of fibrosis, and the serum IGF1/IGFBP-3 ratio decreased with increasing fibrosis." (PMID 36557260, 2022). "Independent from obesity, expression of GHR, IGF-1 and IGFBP-3 was related to AT dysfunction,and increased insulin levels." (PMID 36384443, 2022). "Comparing the mean values of the cohort, children with overweight/obesity were significantly taller compared to lean children and also the serum levels of GHBP, IGF-1 and IGFBP-3 appeared to be increased in children with overweight/obesity." (PMID 36384443, 2022). "Mean concentrations of IGFBP3 and IGFBP4 in the obesity group (OB) were higher than in the control group (HC)." (PMID 34371941, 2021). "Our laboratory and others have shown that obesity increases the serum IGF-1 and lowers IGFBP-3 levels." (PMID 28335515, 2017).
Obesity (continued). "For each SNP, the proportion was estimated using the traits (fasting levels of total and free IGF-I, IGFBP3, insulin, glucose, and HOMA-IR), after stratification by obesity status, level of PA, and exogenous E use." (PMID 29023587, 2017). "However, this reduction is accompanied by a similarly decreased response in circulating IGFBP‐3, resulting in stable levels of free (biologically active) IGF‐1 in the circulation during exercise in humans with obesity." (PMID 40574473, 2025). "However, these correlations were statistically significant only within the subgroup of participants with obesity, possibly indicating a tighter regulation of IGF‐1 and IGFBP‐3 responses in the metabolic context of obesity." (PMID 40574473, 2025). "In our study, serum IGFBP‐3 concentrations increased during exercise in the control study participants without obesity alongside the total IGF‐1, which likely accounts for the absence of an increase in serum free IGF‐1 concentrations." (PMID 40574473, 2025). "Participants with obesity did not display a significant increase in serum IGFBP‐3 concentration in response to exercise at any of the sampling time points." (PMID 40574473, 2025). "The AUC values for serum IGFBP‐3 concentration responses were 5.9‐fold higher up to 15 min (p = 0.05) and 4.7‐fold higher up to 40 (p < 0.05) during exercise in participants without obesity." (PMID 40574473, 2025). "Serum IGFBP‐3 concentration increased during exercise in participants without obesity at both 15 (p < 0.001) and 40 min (p < 0.01) but it was not significantly different from before exercise at 60 min." (PMID 40574473, 2025). "Both total IGF‐1 and IGFBP‐3 serum concentrations increased significantly (p < 0.05) during exercise in the study participants without obesity but not in those with obesity, returning to basal levels immediately after exercise." (PMID 40574473, 2025). "We found that circulating GHBP, and in prepubertal children also IGF-1 but not IGFBP-3 are increased in children with overweight/obesity independently from age and sex." (PMID 36384443, 2022). "As children with overweight/obesity showed reduced gene expression of GHR, IGF-1 and IGFBP-3 in subcutaneous adipocytes and SVF cells, we next analysed if local expression of these factors in adipocytes and SVF cells was associated with parameters of AT function." (PMID 36384443, 2022). "In a recent study conducted in an adult population, patients with higher levels of serum IGF1 and with a higher IGF1/IGFBP-3 ratio had a lower risk of NASH, while patients with obesity with/without MAFLD always had lower serum IGF1 levels." (PMID 36557260, 2022). "It was interesting to observe that while the levels of both IGFBP-3 and -7 were not affected by obesity, they correlated negatively with Ox-LDL level." (PMID 34394011, 2021). "In both sexes, circulating levels of free IGF1, total IGF1, IGF2 and IGFBP3 are reported to be increased in humans and rodents with obesity, although some studies found no changes in total IGF1 in patients with obesity." (PMID 33202914, 2020). "The objectives of this study were to investigate the effects of obesity and DHEA feeding on liver steatosis, body weight gain, and serum DHEA, DHEA sulfate (DHEA-S), insulin-like growth factor-1 (IGF-1), and insulin-like growth factor binding protein-3 (IGFBP-3) levels." (PMID 28335515, 2017). "While the effects of high-fat feeding in the absence of IGFBP-3 have previously been studied, the consequent effects of obesity on tumor growth have not." (PMID 27448965, 2016). "Our findings show that intra-prostatic levels of IGFBP-3, PSA and waist circumference, but not overall obesity, are positively associated with prostate volume." (PMID 24367483, 2013). "In summary, our findings show that intra-prostatic levels of IGFBP-3, PSA and waist circumference, but not overall obesity, are positively associated with prostate volume." (PMID 24367483, 2013).
Obesity (continued). "However, a concurrent attenuation in serum IGFBP‐3 response, which regulates free (i.e., biologically active) IGF‐1 in circulation, results in no change in circulating free IGF‐1 levels during endurance exercise in individuals with obesity." (PMID 40574473, 2025). "Given that IGFBP3 as the inhibitor of IGF1 bioavailability and activity has a vast array of biological functions and is involved in IR, obesity, inflammation, and oxidative stress, it seems reasonable to assume that its gene (IGFBP3) may contribute to the development and progression of NAFLD." (PMID 37948568, 2023). "The transient changes in IGFBP1 and IGFBP3 at 2 weeks after surgery and their relationship to changes in FFA and hsCRP point to a previously unknown link between IGFBPs and adipose tissue function and low-grade inflammation in obesity." (PMID 36959287, 2023). "IGFBP-1 and IGFBP-3 may show no significant change in obesity, or an increase in IGFBP-3." (PMID 36038791, 2022). "Serum levels of free IGF1 and IGFBP3, but not of total IGF1, are reported to be higher and IGFBP2 lower in children with obesity compared to control children." (PMID 32849298, 2020). "While the pathophysiology linking obesity to IGF-1 and IGFBP-3 levels are not completely resolved, data show that increases in visceral fat are associated with elevated levels of serum free fatty acids in the blood." (PMID 26352264, 2015). "In control participants without obesity, serum total IGF‐1 and IGFBP‐3 levels increased in parallel in response to exercise, rising well above pre‐exercise values at both 15 and 40 min into the exercise session, and returning to baseline within 15 min after exercise ended." (PMID 40574473, 2025). "Additionally, the IGF-1/IGFBP-3 ratio, a common rough of free IGF-1 levels, is significantly decreased in obesity, however no IGF-1 bioactivity was estimated." (PMID 26733412, 2016).
ovarian carcinoma (33 papers, 2004 to 2025). A malignant neoplasm originating from the surface ovarian epithelium. "We performed a univariate Cox and survival analysis based on IGFBPs expression in different ovarian cancer patients and the results revealed that IGFBP3/4/5/6 was the risk factor." (PMID 37199034, 2023). "The expression patterns of IGFBP3 and HIFs can be used in the future as diagnostic markers on the invasiveness of ovarian cancer, and on the design for the strategy of target therapy." (PMID 34824343, 2021). "A significant association between IGFBP-3 promoter methylation and disease progression has been reported, but only in early-stage ovarian cancer." (PMID 20003326, 2009). "Moreover, IGFBP3 has been characterized as a suppressor gene of invasion in ovarian cancer and reduced levels of IGFBP-3 are linked to higher tumor grade, advanced stage, and unfavorable clinical prognosis." (PMID 38952983, 2024). "HHV6a integration was also detected at a number of significant genomic sites that may relate to the genesis of ovarian cancer: 1) HHV6a sequences were found integrated 25Kb upstream of the IGFBP3 gene that encodes an IGF-binding protein 3 (IGFBP)." (PMID 28410234, 2017). "However, the association of IGFBP-3 promoter hypermethylation with poor clinical outcome was identified only at early stages in lung and ovarian cancers." (PMID 20003326, 2009). "In ovarian cancer, BRCA1-mut cancer genes such as AIF1, CD8A, and BST1 showed detrimental prognosis, while in BRCA2-mut ovarian cancer, SEC61A2 and IGFBP3 were associated with shorter survival." (PMID 40647506, 2025). "RNA sequencing analysis revealed a potential regulatory role of ULK2 in the insulin signaling pathway through upregulation of insulin-like growth factor binding protein-3 (IGFBP3) in ovarian cancer cells." (PMID 38952983, 2024). "Accordingly, we propose that ULK2 suppresses the migration and growth of ovarian cancer cells through inhibition of the IGFBP3-mediated insulin signaling pathway." (PMID 38952983, 2024). "Our collective findings suggest that ULK2 can diminish ovarian cancer cell proliferation and migration through inducing an increase in IGFBP3 expression." (PMID 38952983, 2024). "In summary, our current research exploratively discovered that ULK2 suppressed cell migration and invasion of ovarian cancer via inhibition of the insulin signaling pathway by promoting upregulation of IGFBP3." (PMID 38952983, 2024). "In summary, the collective data indicated that ULK2 acted as a tumor suppressor in ovarian cancer by upregulating the expression of IGFBP3." (PMID 38952983, 2024). "An increase in IL-3 and IL-10 expressions, insulin-like growth factor binding proteins (IGFBP) IGFBP-1, IGFBP-2 and IGFBP-3 levels were detected in both ovarian cancer cell lines with leptin administration." (PMID 37155466, 2023). "In the CPTAC cohort, IGFBP3, 4, 5, and 6 were significantly downregulated in ovarian cancers, consistent with the mRNA expression levels (p < 0.05)." (PMID 37199034, 2023). "Insulin-like growth factor binding proteins (IGFBP) IGFBP-1, IGFBP-2 and IGFBP-3 were increased by leptin treatment in both ovarian cancer cells." (PMID 37155466, 2023). "Increased IGFBP-3 expression has been demonstrated to negatively correlate with the invasiveness of ovarian cancer in vitro and in vivo." (PMID 36230617, 2022). "MiR-19a-3p targets the expression of IGFBP-3, which is tumor-suppressive in this cancer; thus miR-19a-3p increases the growth and invasiveness of ovarian cancer cells in vitro, and the growth of xenograft tumors in vivo." (PMID 35597813, 2022). "After IGFBP3 was transiently expressed in highly invasive ovarian cancer cell line and heterotransplant on mice, the xenograft tumors demonstrated a transient growth arrest with de-vascularization, causing tumor cell hypoxia." (PMID 34824343, 2021).
ovarian carcinoma (continued). "IGFBP3, which was previously identified as a growth/invasion/metastasis suppressor of ovarian cancer, plays a key role in inhibiting tumor angiogenesis." (PMID 34824343, 2021). "Highly aggressive ovarian cancer cells show lower IGFBP3 and tend to express HIF-2α under hypoxic conditions." (PMID 34824343, 2021). "In support of this notion, IGFBP-3 has shown potential as a metastasis suppressor in prostate, lung, and ovarian cancer." (PMID 33801272, 2021). "The letrozole response is similarly associated with these modified levels of expression in ERα-positive ovarian carcinomas, and this has been confirmed for both IGFBP3 and IGFBP5 in subsequent trials." (PMID 32580290, 2020). "Other studies have observed a relationship between high levels of IGFBP3 methylation and poor clinical outcome in lung and ovarian cancers, and more recently in CRC patients." (PMID 25127039, 2014). "Patients with low IGFBP3 expression and high IGFBP3 promoter methylation have strong correlations with low survival rates in ovarian endometrioid carcinoma, an ovarian cancer subtype." (PMID 24964199, 2014). "Our results demonstrate that the clinical significance of aberrant IGFBP-3 promoter methylation is more commonly observed in the OEC subtype of ovarian cancer." (PMID 20003326, 2009). "By MSP, aberrant methylation at the IGFBP-3 promoter was found in 44% of epithelial ovarian cancer and in 28.6% (12/42) of OEC subtype." (PMID 20003326, 2009). "It was concluded that methylation at IGFBP-3 promoter is a common tumorigenesis process in the early steps of ovarian cancer progression." (PMID 20003326, 2009). "Aberrant promoter hypermethylation of IGFBP-3 and gene silencing are observed in many cancers, such as lung, hepatocellular, gastric, colorectal, breast, and ovarian cancers." (PMID 20003326, 2009). "Recently, we have further identified IGFBP-3 as an invasion suppressor gene using an established ovarian cancer cell line OVTW59-P0 and its sublines P1 to P4, which were obtained from a gradual invasion model with sequential increase in invasiveness." (PMID 20003326, 2009). "Measuring serum levels of IGFBP-3 and IGF1 of healthy women proved useful in predicting a woman's risk of ovarian cancer." (PMID 15471544, 2004). "In ovarian cancer, IGFBP3 inhibits angiogenesis by regulating intracellular THBS1 expression." (PMID 39040110, 2024). "This suggests that IGFBP-3 downregulation may mediate the oncogenic action of high miR-19a-3p expression in ovarian cancer." (PMID 35597813, 2022). "IGFBP-2 and IGFBP-3 are the most common binding proteins involved in ovarian cancer metabolism." (PMID 36230617, 2022). "These suggest OEC is a distinct subtype of ovarian cancer that IGFBP-3 silencing through IGFBP-3 promoter methylation could play an important role in cancer development and progression." (PMID 20003326, 2009). "Moreover, IGFBP3 plays an antiapoptotic effect in ovarian cancer." (PMID 37199034, 2023). "Thus, hyper-methylation of IGFBP-3 is hypothesized as a biomarker for ovarian cancer outcomes, especially for patients in early stages of the disease." (PMID 24782983, 2014). "On the other hand, one study showed that IGFBP-3 may have a protective effect in ovarian cancer." (PMID 18781172, 2008). "In contrast, elevated IGFBP-3 levels may have a protective function in ovarian cancer occurrence." (PMID 18781172, 2008). "These include AIF1, CD8A, and BST1 in ovarian cancer BRCA1-mutant cancers, and SEC61A2 and IGFBP3 in BRCA2-mutant ovarian cancer." (PMID 40647506, 2025). "Compared with IGFBP3, the studies on the relationship between IGFBP5 and ovarian cancer are limited." (PMID 37199034, 2023). "Estrogen down-regulates IGFBP3 and IGFBP5 and up-regulates IGFBP4 in ERα-positive ovarian carcinoma cells." (PMID 32580290, 2020).
ovarian carcinoma (continued). "Although IGFBP3 was highly expressed in IOSE normal ovarian cell line and some ovarian cancer cell lines such as Ovcar3 and SKOV3, IGFBP3 expression was highly downregulated in 2774 and PA-1 cells." (PMID 28008951, 2016). "Diets high in GI and GL could lead to chronic hyperinsulinemia and insulin suppresses IGFBP concentrations; in an Italian case-control study, ovarian cancer was inversely related to IGFBP, in particular to IGFBP-3." (PMID 37221355, 2023). "Increased levels of IGFBP3 are closely associated with an early clinical stage, nonserous histology, optimal cytoreduction, and favorable OS and PFS in epithelial ovarian cancer." (PMID 33282953, 2020).